SUN2 (Sad1 and UNC84 domain containing 2)
Diseases named in the same sentence as SUN2 in open-access papers (continued):
Sharing a sentence is not in itself a finding about the gene and the disease.
prostate carcinoma (3 papers, 2017 to 2023). A carcinoma that arises from epithelial cells of the prostate gland. "SUN2 has recently been identified as a gene whose decreased expression has been significantly associated with prostate cancer in Japanese populations." (PMID 32986714, 2020). "Additionally, we also showed that serum amyloid A1 (SAA1) play a vital role in FAO, ATP and cell growth promoted by Sun2 loss in prostate cancer." (PMID 29163775, 2017). "Additionally, loss of Sun2 promotes the prostate cancer progression by enhancing FAO." (PMID 29163775, 2017). "The Results showed that growth of prostate cancer cells promoted by low Sun2 expression can be reversed by ETO at 10 μmol concentration." (PMID 29163775, 2017). "The results of staining scoring in the 90 prostate cancer tissues and adjacent benign tissues showed that Sun2 expression was downregulated in prostate cancer (61/90,67.5%) (7.24 ± 4.42 vs. 3 .86 ± 3.3, P < 0.05)." (PMID 29163775, 2017). "We identified Sun2 as a gene that is down-expressed in prostate cancer tissues vs.normal tissues, and that low expression of Sun2 was significantly correlated with the high Gleason score, pT, Lymph nodal invasionand clinical pathological stage." (PMID 29163775, 2017). "Next, Sun2 overexpression inhibited the prostate cancer growth, whileSun2 downregulation promoted the prostate cancer growth." (PMID 29163775, 2017). "Consistent with previous report, silencing Sun2 promoted the ATP production of prostate cancer cells." (PMID 29163775, 2017). "In the present study, we found that Sun2 expression was reduced in prostate cancer tissues compared with paired normal tissues, and that low expression of Sun2 was significantly correlated with Higher Gleason scores, postoperative T stage (pT), Lymph nodal invasion and Clinical pathological stages." (PMID 29163775, 2017). "Furthermore, Sun2 mRNA expression was also downregulated (26/35, 74.3%) in prostate cancer patients (P < 0.05)." (PMID 29163775, 2017). "In summary, Sun2 expression is reduced in prostate cancer, and may prove to be a useful predictor of poor clinical outcomes of prostate cancer patients." (PMID 29163775, 2017). "Additionally, decreased Sun2 expression predicts poor survival in prostate cancer and wasan Independent predictor of OS." (PMID 29163775, 2017). "The aim of the present study was to elucidate the expression and role of Sun2 in prostate cancer." (PMID 29163775, 2017). "However, expression and role of SUN2 in prostate cancer is unkown and needs to be explored." (PMID 29163775, 2017). "However, the mechanism of FAO regulated by Sun2 in prostate cancer is unclear." (PMID 29163775, 2017). "And we found that overexpression or knockdown of Sun2 decreased or increased SAA1 expression, respectively, in prostate cancer cells." (PMID 29163775, 2017). "Next, multivariate analysis was performed and the results showed that low Sun2 expression (P < 0.01) and TNM stage (P = 0.02) were the independent factors predicting the prognosis of prostate cancer patients." (PMID 29163775, 2017). "Next, we observed a significant inverse correlation between Sun2 and SAA1 in prostate cancer tissues (P = 0.0019)." (PMID 29163775, 2017). "In order to determine the role of Sun2 in prostate cancer, CRPC cell line pc-3 with relatively low expression Sun2 was transfected with Sun2." (PMID 29163775, 2017). "Our results showed that silencing Sun2 can not increase glucose uptake (data not shown) and the glycolytic rate in prostate cancer cells." (PMID 29163775, 2017). "Here, we showed that low Sun2 expression promoted prostate cancer progression by enhancing FAObut had no significant impact on glycolysis." (PMID 29163775, 2017). "The aim of the present study was to examine the relationship between Sun2 expression and clinicopathologic outcomes by tissue microarray (TMA) of 90 prostate cancer patients, and then investigate the role of Sun2 in prostate cancer cell growth in vitro and in vivo." (PMID 29163775, 2017).
viral infection (3 papers, 2017 to 2024). "Mechanistically, SUN2 facilitates rearrangement of cytoskeleton and formation of replication organelles induced by viral infection, and hence promotes viral RNA synthesis." (PMID 38177122, 2024). "Considering SUN2 is a link protein connecting the nucleoskeleton and cytoskeleton, we hypothesized that SUN2 might direct the rearrangement of cytoskeleton induced by viral infection." (PMID 38177122, 2024). "As both RNA and protein levels of ZIKV were downregulated by SUN2 depletion, we speculated that SUN2 acts at an early step of viral infection." (PMID 38177122, 2024).
dilated cardiomyopathy (2 papers, 2020 to 2024). Cardiomyopathy which is characterized by dilation and contractile dysfunction of the left and right ventricles. "In Emery–Dreifuss muscular dystrophy and dilated cardiomyopathy patients, mutations in SYNE1 have been found, which affects nuclear morphology and impairs protein-protein interaction with lamin A/C and SUN2." (PMID 33330489, 2020).
esophageal cancer (2 papers, 2015 to 2025). A primary or metastatic malignant neoplasm involving the esophagus. "Prior research has reported the negative effect of CBY1 and SUN2 genes on tumorigenesis, which implied a potential role of them in the pathogenesis of gallstone disease and GERD, given that these 2 diseases are risk factors for gallbladder and esophageal cancer, respectively." (PMID 40139907, 2025).
laminopathies (2 papers, 2022 to 2025). "Whereas SUN1 and SUN2 have both been reported to interact with lamin A, they appear to have different roles in lamin A mutation-associated laminopathies including Emery–Dreifuss muscular dystrophy (EDMD) and Hutchinson–Gilford progeria syndrome (HGPS), as well as in mammalian development." (PMID 34983624, 2022).
triple-negative breast carcinoma (2 papers, 2021 to 2024). An invasive breast carcinoma which is negative for expression of estrogen receptor (ER), progesterone receptor (PR), and human epidermal growth factor receptor 2 (HER2). "Reducing and non-reducing SDS-PAGE analyses revealed a prevalence of SUN2 homodimers in non-tumorigenic breast epithelia MCF10A cells, but not in the invasive triple-negative breast cancer MDA-MB-231 cell line." (PMID 38891038, 2024).
alopecia (1 paper, 2017). Hair loss usually from the scalp. "Deletion of Sun2, a functional homologue of Sun1, also showed aberrant nuclear position, altered desmosome distribution, and mechanically defective adhesions resulting in defective hair follicle structure and alopecia." (PMID 28595999, 2017).
bipolar disorder (1 paper, 2015). A disorder of the brain that causes unusual shifts in mood, energy, activity levels and the ability to carry out day-to-day tasks. "Therefore, future research addressing whether mice that are deficient in Sun1 and/or Sun2, or Syne1 and/or Syne2 show cognition phenotypes such as schizophrenia or bipolar disorder could be beneficial in the field of psychiatric medicine." (PMID 26035387, 2015).
breast tumor (1 paper, 2015). "The results showed that expression of SUN1, SUN2, nesprin-2, and lamin A/C mRNA in breast tumor was lower than mammary gland tissue." (PMID 26175118, 2015).
cerebellar ataxia (1 paper, 2015). A neurological syndrome characterized by clumsy and uncoordinated movement of the limbs, trunk, and cranial muscles. "Our findings reveal a cell-type-specific role for Sun1 and Sun2 in nucleokinesis during cerebellar development, and we propose the use of Sun-deficient mice as a model for studying cerebellar ataxia that is associated with mutation of human SYNE genes or loss of Purkinje cells." (PMID 26035387, 2015).
cholelithiasis (1 paper, 2025). The presence of crystallized deposits forming in the gallbladder or biliary tree, primarily composed of cholesterol, bilirubin, and bile. "In general, we identified 3 putatively functional genes shared between cholelithiasis and GERD, including SUN2, CBY1, and JOSD1, overexpression of which was negatively associated with the risk of cholelithiasis and GERD in the esophagus-related tissues." (PMID 40139907, 2025). "The TWAS analysis showed that overexpression of SUN2, JOSD1, and CBY1 was negatively associated with the risk of cholelithiasis and GERD in the blood and esophagus-related tissues, while overexpression of JOSD1 and CBY1 was positively associated with these 2 diseases in the liver tissue." (PMID 40139907, 2025).
cytomegalovirus infection (1 paper, 2026). A herpesvirus infection caused by Cytomegalovirus. "Consistent with our studies, the infection-induced decrease in SUN2 has been detected in HSV-1 and human cytomegalovirus infections." (PMID 41557685, 2026).
emerinopathies (1 paper, 2019). "It will now be interesting to determine whether SUN2 deficiency promotes cardiac fibrosis, as well as to explore the expression of SUN2 in other experimental models of emerinopathies." (PMID 31185657, 2019).
Flavivirus Infections (1 paper, 2024). Infections with viruses of the genus FLAVIVIRUS, family FLAVIVIRIDAE. "This work elucidates that recruitment of cytoskeleton proteins by flavivirus is coordinated by nuclear membrane proteins SUN2 and Nesprins, providing evidence for a link between nuclear membrane proteins and flavivirus infection." (PMID 38177122, 2024).
hypertrophic cardiomyopathy (1 paper, 2014). A condition in which the myocardium is hypertrophied without an obvious cause. "We also identified two SUN2 variants, encoding variants p.M50T and pV378I, in patient MD-2 who had hypertrophic cardiomyopathy and also carried a mutation in MYBPC3 (p.G148R), which encodes a myosin binding protein." (PMID 25210889, 2014).
invasive breast carcinoma (1 paper, 2025). A carcinoma that infiltrates the breast parenchyma. "Lower lamin A/C and lamin B1 expression; decreased levels of emerin in invasive breast cancer; downregulation of SUN1, SUN2, and nesprin‐2; upregulation of LBR." (PMID 39866838, 2025).
microcephaly (1 paper, 2024). A congenital or acquired developmental disorder in which the circumference of the head is smaller than normal for the person's age and sex. "Severe paralysis and microcephaly were observed in the ZIKV-infected WT mice, which was significantly abrogated in Sun2-/- mice." (PMID 38177122, 2024).
non-small cell lung carcinoma (1 paper, 2025). A group of at least three distinct histological types of lung cancer, including non-small cell squamous cell carcinoma, adenocarcinoma, and large cell carcinoma. "Studies have shown that SIRT5 is highly expressed in non-small cell lung cancer (NSCLC), and inhibition of SUN2 promotes cancer cell proliferation." (PMID 39979670, 2025).
osteosarcoma (1 paper, 2025). A usually aggressive malignant bone-forming mesenchymal neoplasm, predominantly affecting adolescents and young adults. "A recent study delved into the mechanism that governs SUN2 turnover, shedding light on how the buildup of nondegradable forms of SUN2 led to the disruption of nuclear architecture in Hela cells and impeded the repair of DSBs (double‐strand breaks) in osteosarcoma cells exposed to ionizing radiation." (PMID 39866838, 2025).
ZIKV infection (1 paper, 2024). "In a neonatal mice model, SUN2 knockout leads to significant reductions of in vivo viral replication levels and severity of neuropathogenesis induced by ZIKV infection." (PMID 38177122, 2024). "In response to ZIKV infection, the SUN2 protein levels in Huh7 cells were gradually decreased at 24 and 48 h post-infection (h p.i)." (PMID 38177122, 2024). "To examine whether the localization of Nesprins is altered by ZIKV infection and whether SUN2 is required for their movement, we carried out IFM assay." (PMID 38177122, 2024). "To probe whether SUN2 promotes the ZIKV infection through modulating the reorganization of cytoskeleton, we compared viral replication levels in the absence and presence of individual inhibitors of cytoskeleton proteins." (PMID 38177122, 2024). "Our findings that the cytoplasmic part of Nesprin-1 moves to the perinuclear region and colocalizes with viral protein upon ZIKV infection in a SUN2-dependent manner demonstrated that the virus-induced cytoskeleton movement needs a mechanical support from LINC proteins." (PMID 38177122, 2024). "Importantly, our data demonstrated that SUN2 plays a critical role in the remodeling of cytoskeleton network induced by ZIKV infection, although their loss does not affect the cytoskeletal structure in latent cells." (PMID 38177122, 2024). "Upon ZIKV infection, both calnexin and SEC61B were aggregated around the nuclei and co-localized with ZIKV E protein in the control cells, while SUN2 KO significantly dampened their aggregation." (PMID 38177122, 2024). "To explore whether SUNs participate in ZIKV infection, we generated two SUN1 and SUN2 knockout cell clones in Huh7 cells by CRISPR/Cas9 gene-editing technique." (PMID 38177122, 2024).
cancer (23 papers, 2013 to 2025). A tumor composed of atypical neoplastic, often pleomorphic cells that invade other tissues. "In line with this, SUN2 overexpression decreases lung cancer cell proliferation and migration and makes cancer cells more susceptible to cisplatin-induced apoptosis." (PMID 36980194, 2023). "Several LINC-associated proteins such as SUN1, SUN2, Emerins and Nesprin-3 were seen to be differentially regulated in cancer cells exposed to simulated microgravity." (PMID 32942630, 2020). "And ENST00000418803 associated gene Sad1 and UNC84 domain containing 2 (SUN2) act as novel suppressors in cancer." (PMID 31355249, 2019). "Dysregulation of Sun2, as a characteristic NE protein, is associated with many human diseases, including cancers." (PMID 29163775, 2017). "SUN2 homeostasis thus appeared critical for cancer progression, as the heightened degradation of SUN2 via ubiquitination led to increased proliferation of ovarian cells and inhibited apoptosis." (PMID 39866838, 2025). "Changes in the levels of SUN proteins, particularly SUN1 and SUN2, also influence cancer cell migration, with tumor type‐dependent effects." (PMID 39866838, 2025). "SAD1/UNC84 domain protein-2 (SUN2) plays a tumor suppressor role in various types of cancer by inhibiting cancer cell proliferation, migration and promoting apoptosis." (PMID 35525855, 2022). "The results showed that Sun2 overexpression promoted the cancer cell apoptosis (P < 0.05) and induced cell cycle arrest in G1/S phase (P < 0.05) compared with the control." (PMID 29163775, 2017). "Recent studies reported that Sun2 expression was downregulated in various cancers and also played a pivotal role in cellular biological pathways." (PMID 29163775, 2017). "SUN2 acts as a tumor suppressor since its activity counteracts the Warburg effect, a metabolic change in which glycolysis predominates over oxidative phosphorylation as the major source of ATP, providing rapid energy to drive cancer cell growth." (PMID 36980194, 2023). "Furthermore, we found that Sun2 overexpression inhibited the cancer cell proliferation by CCK-8 evaluation at 48 and 72 h (P < 0.05)." (PMID 29163775, 2017). "The effect of Sun2 knockdown on rostate cancer cells proliferation was evaluated using CCK-8 kit." (PMID 29163775, 2017). "To further investigate the link between SUN proteins, nuclear shape and motility in carcinoma cells, we disrupted LINC complex by knocking down SUN proteins (SUN1 and SUN2)." (PMID 34205257, 2021). "This quantitation revealed that for all four proteins, most cancer tissues were in the low expression group: 85.1%, 88.4%, 74.4%, and 79.2% for lamin A/C, SUN1, SUN2, and nesprin-2, respectively." (PMID 26175118, 2015). "In many cases, the staining intensities of SUN1, SUN2, and nesprin-2 were often weaker in cancer cells (middle column) than in noncancerous regions (left column); again, however, some cases exhibited normal expression (right column)." (PMID 26175118, 2015). "Anti-lamin A/C, anti-SUN1, anti-SUN2, and anti-nesprin-2 pAbs clearly stained noncancerous acini of terminal-duct lobular units adjacent to cancer cells at the nuclear membrane." (PMID 26175118, 2015). "Previous studies showed that SUN1, but not SUN2, is the main interactor of KASH-domain proteins in the LINC complex assembly and depleting SUN1 inhibits NE rupture in cancer cell lines." (PMID 39209536, 2024).
tumor (12 papers, 2015 to 2026). "Similarly, the SUN2 gene, which has distinct tumor-specific functions, has also been implicated in these interactions." (PMID 38627780, 2024). "SUN2 can function as a tumor suppressor by inhibiting cell proliferation in embryonal cancers of the central nervous system and inhibiting cell migration of lung cancer cells." (PMID 39866838, 2025). "Among those glycosylated proteins, we focused on SUN2 protein, as it plays a tumor suppressor role in a variety of tumor cells by promoting apoptosis." (PMID 35525855, 2022). "Analysis using The Cancer Genome Atlas (TCGA) and the Genotype-Tissue Expression (GTEx) datasets showed downregulated expression of SUN1 and SUN2 across tumor types." (PMID 35663386, 2022). "Both miRNAs regulate the expression level of the target gene SUN2, which is a tumor suppressor and accelerates cell proliferation and tumor malignancy both in vitro and in vivo." (PMID 34552822, 2021). "Analysis of The Cancer Genome Atlas dataset showed a dramatic decrease in the LINC complex proteins SUN1 and SUN2 in primary tumor compared to the normal tissue." (PMID 34205257, 2021). "It was found that the mean tumor weight was significantly reduced in Sun2 overexpression tumors compared with vector control tumors (p < 0.05)." (PMID 29163775, 2017). "Mechanistically, we showed that SUN2 exerts its tumor suppressor functions by decreasing the expression of GLUT1 and LDHA to inhibit the Warburg effect." (PMID 26658802, 2015). "SUN1 and SUN2 were recently identified as crucial mediators in remodeling the nucleus of macrophages during M1 polarization in response to inflammatory signals—a tightly regulated process whose imbalance often correlates with tumor progression." (PMID 39866838, 2025). "In this context, SUN2 acts as a tumor suppressor by downregulating the expression of brain‐derived neurotrophic factor (BDNF), thus inhibiting the BDNF/tropomyosin‐related kinase B signaling whose overexpression seemed involved in several carcinogenic processes." (PMID 39866838, 2025). "SUN2 also interacts with lamins, functioning as a nuclear skeleton in the neoplasm." (PMID 37612283, 2023). "SUN1 and SUN2 are downregulated in tumors and exert tumor-suppressive effects." (PMID 36358787, 2022). "Recent studies have shown that SUN2 inhibit a variety of tumor malignancies in vitro and in vivo." (PMID 29163775, 2017). "Moreover, downregulation of SUN1 and SUN2 was observed across tumor types." (PMID 34205257, 2021). "Using smartpool siRNAs for SUN1 and SUN2, we efficiently knocked down SUN1 and SUN2 (referred to SUN1 + 2 KD hereafter) in tumor cells." (PMID 34205257, 2021). "In fact, using triple knockdowns (SUN1, SUN2, and MKL1) in tumor cells, we show that MKL1 is required for enhanced 1D motility of SUN1 + 2 KD cells." (PMID 34205257, 2021). "We treated tumor cell with either control siRNA or siRNAs for SUN1, SUN2 and MKL1." (PMID 34205257, 2021).